CD36 (CD36 molecule (CD36 blood group))
Diseases named in the same sentence as CD36 in open-access papers (continued):
Sharing a sentence is not in itself a finding about the gene and the disease.
Hepatic steatosis (continued). "The significance of CD36 in the pathogenesis of NAFLD onset has been studied because modulation of its expression in the liver directly effects hepatic steatosis." (PMID 36594091, 2023). "When coupled with a high-fat diet (HFD), BPA exposure worsens hepatic steatosis by stimulating ROS-induced overexpression of Cd36 (fatty acid translocase) in the mouse liver, thus facilitating lipid uptake." (PMID 37242221, 2023). "CD36 deletion in hepatocytes reduced HFD-induced hepatic steatosis, decreased hepatic fatty acid uptake, and improved whole-body insulin sensitivity." (PMID 37764494, 2023). "Higher levels of respective CD36 are a biomarker of high-fat diet-induced hepatic steatosis, and its reported knockdown improved insulin sensitivity and steatosis owing to observed decrease in FA uptake and TAGs concentration." (PMID 36771233, 2023). "CD36 is a target of PPARγ, and it is suggested that ERK signaling activates CD36 expression through PPARγ in hepatic steatosis." (PMID 36410795, 2023). "Administration of L. intestinalis reversed the impairment in glucose tolerance as well as increment in plasma triglyceride, lipid absorption, intestinal Cd36 (P = 0.0008), liver steatosis measured by oil red O and H&E staining, and adiposity." (PMID 36631606, 2023). "In this regard, in a preclinical work, after the complete ablation of the Cd36 gene in ob/ob mice, the animals developed severe hepatic steatosis." (PMID 37628929, 2023). "Although some reports suggest that TH increases the activity of hepatic lipases, lipophagy, and β-oxidation of fatty acids, which help fatty liver to reduce steatosis, little changes were found here in genes involved in fat oxidation (CPT1a, CD36, and AOX)." (PMID 37649581, 2023). "Increased fatty acid uptake has been directly related to the increased hepatic CD36 under high-fat diet (HFD)–induced hepatic steatosis in mice." (PMID 36410795, 2023). "The strong induction of hepatic CD36 likely represents a key mechanism promoting fatty liver disease by increasing uptake of free fatty acids (FFA) as well as expression of de novo lipogenic genes." (PMID 38024380, 2023). "CD36 is a receptor which mediates uptake of long chain FAs in multiple tissues, and deletion of hepatic CD36 in mice results in protection from hepatic steatosis and inflammation." (PMID 36243100, 2022). "CD36 and PPAR-γ play key roles in lipid-homoeostasis and increased hepatic mRNAs have been associated with abnormal storage of fat and hepatic steatosis." (PMID 35685773, 2022). "As a key gene responsible for regulating lipid uptake in hepatocytes, the expression level of CD36 is closely related to the pathological process of fatty liver and insulin resistance." (PMID 35520273, 2022). "In our study, increased hepatic steatosis in HFD-fed S1PR3−/− mice was mechanistically related to elevated expression of CD36, a fatty acid transporter and the lipogenic transcription factor SREBP1c." (PMID 35094654, 2022). "A previous study showed Cd36 null mice are protected from hepatic steatosis induced by Lxr agonists and that Cd36 is a common target of Lxr, as well as Pparγ and pregnane X receptor." (PMID 35406736, 2022). "A previous study showed that mice fed an HFD displayed induced hepatic steatosis and increased expression of CD36." (PMID 35198905, 2022). "CD36 silencing ameliorates lipid accumulation and improves hepatic steatosis by restoring the reduction in fatty acid oxidation in vitro." (PMID 35592528, 2022). "For example, it was shown that PCSK9 knockout mice develop hepatic steatosis after high-fat diet related to increased expression of CD36 on hepatocytes." (PMID 35050192, 2022). "In the condition of high expression of CD36, a large amount of fatty acid can be synthesized and then promote the development of fatty liver." (PMID 35592528, 2022).
Hepatic steatosis (continued). "Differently, our study uncovered the novel molecular mechanisms of Alisol B on hepatic steatosis and lipotoxicity via regulating RARα-PPARγ-CD36 transcriptional cascade." (PMID 35745142, 2022). "The correlation between CD36 levels and the storage and secretion of triglyceride suggests that CD36 plays an initiating role in hepatic steatosis." (PMID 36111293, 2022). "JAK2L mice with increased FFA concentrations show a significantly increased expression of hepatic CD36 and fatty liver disease." (PMID 36209101, 2022). "In contrast, lack of colonization with the protective Clostridia in germ-free mice resulted in elevated CD36 expression, weight gain, fatty liver disease, adipose tissue inflammation, and insulin resistance." (PMID 35334900, 2022). "Based on the indications provided by these data, we further revealed that cd36 plays a crucial role in regulating extrahepatic fatty acid uptake and inducing hepatic steatosis during starvation conditions." (PMID 33513687, 2021). "As a common target of lipogenic nuclear receptors, CD36 plays an important role in HFD-induced hepatic steatosis by modulating the rate of fatty acid uptake." (PMID 34073834, 2021). "To further explore the role of cd36 in starvation-induced hepatic steatosis, we successfully created two independent mutant lines using the CRISPR/Cas9 system in zebrafish." (PMID 33513687, 2021). "Increased expression of hepatic CD36 leads to lipid accumulation, whereas inhibition of CD36 is resistant to hepatic steatosis." (PMID 33513687, 2021). "CD36 is an important mediator of lipid uptake in many tissues, and abnormal CD36 expression in the liver resulted in TG accumulation and the development of hepatic steatosis." (PMID 34822586, 2021). "Activation of AHR can induce CD36 expression, enhance fatty acid uptake, and lead to hepatic steatosis." (PMID 34803486, 2021). "In mouse models of metabolic disease, hepatic overexpression of CD36 increases liver triglyceride storage, whereas the liver specific disruption of CD36 attenuates the development of fatty liver under HFD." (PMID 34488621, 2021). "TMP alleviated hepatic steatosis (lipid contents and lipid droplets) in high-fat-fed mice and down-regulated the PPARγ, CD36, and DGAT2 gene levels." (PMID 33807173, 2021). "We also demonstrated that the degree of hepatic steatosis in animals can be reduced by targeting the inhibition of the expression of cd36 under starvation conditions." (PMID 33513687, 2021). "In the rat model of hepatic steatosis, CD36 level was positively correlated with TGs content in the liver." (PMID 34604283, 2021). "CD36 localization on the plasma membranes of hepatocytes was markedly increased in patients with NASH as compared to people with normal livers or simple hepatic steatosis, in which CD36 palmitoylation plays a key role via increased CD36 protein hydrophobicity." (PMID 33923817, 2021). "Surprisingly, Tim-1-/- mice on HFD diet exhibited an exacerbation of hepatic steatosis, accompanied with an elevation of protein levels of fatty acid translocase CD36 and sterol regulatory element binding protein 1 (SREBP1)." (PMID 34675931, 2021). "In rodents, the hepatocyte specific disruption of CD36 attenuates the development of fatty liver diseases and insulin resistance induced by a HFD." (PMID 34488621, 2021). "Further it is reported that deletion of Cd36 improved hepatic steatosis, insulin sensitivity, and reduced systemic inflammation." (PMID 31921324, 2020). "Castration-induced testosterone deficiency predisposed animals on ND to early development of fatty liver by activating fatty acid (FA) synthesis, whereas HFD activated hepatic FA uptake CD36 expression, leading to the development of hepatic steatosis." (PMID 32807074, 2020). "It transcriptionally upregulates the fatty acid transporter CD36 to enhance fatty acid uptake in hepatocytes, thereby promoting liver steatosis." (PMID 33173745, 2020).
Hepatic steatosis (continued). "Klf2 is known to promote hepatic steatosis through upregulation of Cd36 expression and Klf2 mRNA expression was increased in rats fed high Cho." (PMID 31921324, 2020). "Deleting Degs1 from adult mice either prevented or reversed hepatic steatosis in ob/ob mice by blunting lipid uptake (via the fatty acid translocase CD36) and decreasing expression of lipogenic genes (e.g., Srebf1)." (PMID 32849291, 2020). "In contrast, mice with hepatocyte-specific Cd36 deletion were protected against HFD-induced liver steatosis and, even, improved whole-body insulin sensitivity." (PMID 32978374, 2020). "An increased hepatic NEFA influx through specific membrane translocases, such as CD36, eventually induces enhanced hepatic steatosis also in the NASH‐HCC mouse model in use, upon genetic OPN deletion." (PMID 32281248, 2020). "The significance of CD36 in the pathogenesis of NAFLD onset has been demonstrated because modulation of its expression in the liver directly affects hepatic steatosis." (PMID 32978374, 2020). "In fact, a hepatocyte-specific CD36 knockout model demonstrated an attenuation of hepatic steatosis and improved insulin sensitivity." (PMID 31805072, 2019). "Fatty acid uptake and TAG synthesis were involved in VPA-induced hepatic steatosis by increasing the expression of CD36 and DGAT2." (PMID 31379584, 2019). "Previous studies show that AhR as well as PXR induces liver steatosis through induction of CD36, a fatty acid transporter." (PMID 31681434, 2019). "CD36 is a scavenger receptor central to the hepatic uptake of fatty acids and the pathogenesis of fatty liver disease." (PMID 31877869, 2019). "Hepatocyte-specific conditional deletion of Cd36 in mice was shown recently to greatly attenuate lipid accumulation in two models of hepatic steatosis." (PMID 29351395, 2018). "The expression of CD36 is low in normal hepatocytes but is upregulated by lipid-rich diets, hepatic steatosis, and NAFLD." (PMID 30037134, 2018). "In our study, we found that, despite of the development of hepatic steatosis, the expression of Cd36 in the CR‐MF group remains low, comparable to the expression levels in the lifelong CR diet group." (PMID 29266667, 2018). "As illustrated by the analysis of Cav1, Fabp4, and Cd36 expressions and their relations with hepatic steatosis, the liver has a robust metabolic network that includes multiple regulators contributing its plasticity in coping with the challenge of MF diet." (PMID 29266667, 2018). "In contrast, hepatic levels of CD36 were found to be similar in morbidly obese women with hepatic steatosis compared to morbidly obese controls with normal livers." (PMID 29936596, 2018). "Mice fed a high fat diet develop hepatic steatosis alongside increased mRNA and protein expression of CD36." (PMID 29936596, 2018). "Chlorogenic acid was reported to curb hepatic steatosis, which correlated to suppression on hepatic gene expression of peroxisome proliferator-activated receptor γ, CD36, and fatty acid binding protein 4 induced by HFD." (PMID 30618733, 2018). "Emerging evidence has also suggested a crucial role of CD36 in the pathogenesis of fatty liver disease and other metabolic disorders." (PMID 30544997, 2018). "Taken together, the protective effects of Curc-mPEG454 against hepatic steatosis are possibly via specific inhibition of PPAR-γ/CD36 pathway activation and subsequent reduction of FFA uptake and TG synthesis in the liver." (PMID 28770225, 2017). "Hepatocyte-specific disruption of CD36 attenuates fatty liver disease and improves insulin sensitivity in HFD-fed mice." (PMID 28578672, 2017). "It has been shown that the upregulation of CD36 in the liver is associated with increased steatosis in NAFLD patients and CD36−/− mice are resistant to alcohol and high carbohydrate-induced hepatic steatosis." (PMID 28101297, 2016). "Based on these studies, we investigated the involvement of PPARγ- and CD36-regulated lipid metabolism in VPA-induced hepatic steatosis." (PMID 27034954, 2016).
Hepatic steatosis (continued). "To further confirm the importance of CD36 in VPA-induced hepatic steatosis, we analyzed cell-surface CD36 levels using flow cytometry analyses." (PMID 27034954, 2016). "The expressions of PPARγ, FSP27 and CD36 decreased with the suppression of hepatic steatosis in the LIrs1KO mice, whereas they were maintained in the LIrs2KO mice." (PMID 27708333, 2016). "Increased Cd36 mRNA expression has been found to correlate with increased hepatic TAG content in different models of hepatic steatosis." (PMID 26047317, 2015). "CD36 functions in the development of hepatic steatosis in rodents, and is the most well-characterized free fatty acid transporter." (PMID 25310357, 2014). "Our data are in line with previous findings confirming a role for CD36 in hepatic fatty acid uptake and hepatic steatosis in both rodents and NAFLD patients." (PMID 24751397, 2014). "Nrf2-null mice exhibited more severe hepatic steatosis, while Keap1-KD mice exhibited less, along with decreased CD36 and Fgf21 expression, suggesting Nrf2 negatively regulate lipogenesis and hepatic lipid accumulation." (PMID 24224011, 2013). "Excessive fatty acid uptake mediated by fatty acid translocase CD36 plays an important role in hepatic steatosis." (PMID 23448206, 2013). "It is of interest that hepatic steatosis affected the localization of CD36 protein in the hepatocytes." (PMID 24016701, 2013). "There is extensive evidence showing that CD36 plays significant roles in hepatic steatosis, suggesting that CD36 can be a potential drug target against NAFLD." (PMID 23448206, 2013). "CD36 was drastically enhanced in a HFD-induced fatty liver and nonalcoholic fatty liver in humans, and these elevated levels of CD36 expression correlated with hepatic fat contents." (PMID 22363472, 2012). "We found that hepatic steatosis was alleviated in CD36−/− mice fed with HFD." (PMID 40110132, 2025). "However, the administration of endogenous agonists of AhR such as cinnabarinic acid (CA) down-regulated CD36 and reduced the uptake of free fatty acids in hepatocytes, thus achieving the inhibition of hepatic steatosis and liver injury." (PMID 39944639, 2025). "However, when CD36 is specifically knocked out in the liver of mice, these animals exhibit resistance to the development of liver steatosis induced by an HFD." (PMID 40110132, 2025). "In mouse models, genetic deletion of CD36 mitigates high-fat diet (HFD)-induced hepatic steatosis." (PMID 41306774, 2025). "To gain further insight into the underlying causes of hepatic steatosis induced by chronic HFD consumption, we investigated the expression profiles of major regulatory genes necessary for hepatic lipid metabolism (FASN, ACC1, SCD1, SREBP-1c, and CD36)." (PMID 40076869, 2025). "Despite the well-documented function of CD36 in fatty acid uptake and the close association of CD36 with the development of NAFLD, hepatic overexpression of CD36 unexpectedly attenuates HFD-induced hepatic steatosis and insulin resistance." (PMID 39774047, 2025). "Hence, we can conclude that YBX1 enhances hepatic lipid uptake by positively regulating the transcription of CD36 and exerts a pivotal role in liver steatosis." (PMID 40083711, 2025). "Similarly, treatment with the FXR agonist GW4064 reduces hepatic steatosis and weight gain by suppressing the expression of CD36, a key lipid transporter." (PMID 41438090, 2025). "Several CD36-related studies have indicated that liver steatosis is more severe in CD36−/− mice." (PMID 39774047, 2025). "Additionally, hepatic AHR activation induces CD36 gene expression and increases fatty acid uptake, promoting hepatic steatosis." (PMID 39866414, 2025). "Taken together, we speculate that LG attenuates DXM-induced fatty liver, at least in part, by downregulating the expression of CD36 and FASN." (PMID 39820544, 2025).
Hepatic steatosis (continued). "Additionally, multiple studies have shown that CD36 can influence various pathological processes, such as ovarian cancer and fatty liver disease, through ferroptosis." (PMID 41000398, 2025). "Moreover, administration of PPARγ antagonist T0070907 mitigated the hepatic Cd36 and Cidea/c increase and improved Snhg3-induced hepatic steatosis." (PMID 39436790, 2024). "In humans, PRL has also been shown to ameliorate hepatic steatosis via the CD36 pathway." (PMID 39682330, 2024). "Cd36 and Slc27a2 are both involved in lipid synthesis and oxidation, and fatty acid metabolism, oxidation; and only Cd36 is involved in fatty acid transport and hepatic steatosis." (PMID 38787127, 2024). "In the liver, PRL ameliorates hepatic steatosis via the CD36 pathway." (PMID 39682330, 2024). "Furthermore, inhibition of PPARγ with T0070907 alleviated Snhg3- and SND1-induced Cd36 and Cidea/c increase and improved Snhg3-aggravated hepatic steatosis." (PMID 39436790, 2024). "In hepatic steatosis mice, CD36 deletion reduced liver lipid content and could also contribute to improved insulin sensitivity." (PMID 39524404, 2024). "In addition, this study showed that clopidogrel alleviated hepatic steatosis, probably through restraining CD36-mediated fatty acid uptake, consistent with a previous finding that clopidogrel downregulates the expression of CD36." (PMID 39508046, 2024). "In addition, SSO treatment inhibited the gene expression level of CD36 in the liver and ameliorated hepatic steatosis induced by HFS." (PMID 37305546, 2023). "Furthermore, a previously published study demonstrated the alleviating effects of R. intestinalis on alcoholic fatty liver and suggested that these effects were associated with a significant decrease in PPAR-γ and CD36 levels." (PMID 37674003, 2023). "Also, the severity of hepatic steatosis positively and significantly correlated with hepatic CD36 expression and negatively correlated with DNA CpG methylation of hepatic Cd36 P2 and P3, suggesting a conserved mechanism between the sexes." (PMID 37479748, 2023). "In addition, it is also reported that CD36 is a shared downstream target of LXRα, PXR and PPARγ, and that LXRα-mediated CD36 induction is responsible for T0901317 treatment-mediated hepatic steatosis, which was abrogated in CD36 KO mice." (PMID 37174692, 2023). "In fact, CD36 expression is much lower in normal hepatocytes than in hepatic steatosis and NAFLD." (PMID 37509601, 2023). "An increased hepatic CD36 expression can enhance fatty acid uptake and triglyceride accumulation, although the precise role of CD36 in the pathogenesis of fatty liver remains unclear." (PMID 37509601, 2023). "Icariin improves hepatic steatosis in PCOS rats via the CD36-PPARα pathway." (PMID 36677577, 2023). "Similarly, in our study, we observed a significant decrease in PPAR-γ and CD36 levels in the group treated with K. alysoides, which exhibited alleviation of fatty liver." (PMID 37674003, 2023). "Therefore, an HF diet can induce higher expression of inflammatory cytokines and upregulate the protein expression levels of FASN, ACC1, CD36, ChREBP, and SREBP1c, thereby promoting the development of the fatty liver." (PMID 37095192, 2023). "Moreover, quantitative reverse transcriptase PCR (qRT-PCR) analysis revealed that the mRNA level of Cd36 was significantly upregulated in the liver of four different kinds of fatty liver disease mouse models." (PMID 37335109, 2023). "To explore the mechanisms involved in GPR40 KO-associated hepatic steatosis, we hypothesized that GPR40 KO may lead to upregulation of CD36, another receptor for FFAs." (PMID 36331958, 2022). "An early study has identified that RARα overexpression alleviated hepatic steatosis via suppressing HNF4α-regulated PPARγ expression, but whether CD36 is involved in RARα’s regulation on hepatic lipid metabolism is unknown." (PMID 35745142, 2022). "CD36 is a transcriptional target of PPARγ in promoting hepatic steatosis." (PMID 35682942, 2022).